ID3 (inhibitor of DNA binding 3)
Diseases named in the same sentence as ID3 in open-access papers (continued):
Sharing a sentence is not in itself a finding about the gene and the disease.
tumor (continued). "Three tumor types, namely PRAD, TGCT and KIRP, showed direct correlation between ID3 expression and the enrichment score of HR-related pathways." (PMID 34718742, 2021). "To identify the impact of low ID3 expression on DSB repair particularly by HR in tumors, we used TCGA gene expression data of various tumor entities." (PMID 34718742, 2021). "Conversely, depletion of Id1 and Id3 in the 4T1 murine model of TNBC demonstrates that Id1/3 are required for cell proliferation and self-renewal in vitro, as well as primary tumor growth and metastatic colonization of the lung in vivo." (PMID 32766238, 2020). "Overexpression of ID3 gene correlated with decreased in CD38 expression and greater complexity of tumor cells (SSC)." (PMID 28245840, 2017). "Finally, we have also shown that in GC, ID3 is likely a downstream effector of Dies1, and that GC myofibroblasts overexpress Dies1, which may be acting together with immune cells to refrain the anti-tumoral immune response, enabling tumour growth." (PMID 27721458, 2016). "Previously, we have found that Id3 induced apoptosis in immortalized human keratinocytes upon UVB exposure, consistent with its role as a tumor suppressor." (PMID 25693514, 2015). "EGFR signaling regulates the proliferation and tumorigenic ability of GSCs by inducing ID3 and ID3-regulated cytokines (GRO1, IL-6, and IL-8), which play a crucial role to make the tumor microenvironment suitable for GSC maintenance." (PMID 26437223, 2015). "Like FAS, ID over-expression correlates with tumor development in an array of cancers, and knockdown of ID2/ID3 induces growth arrest and apoptosis." (PMID 17565694, 2007). "The same knockdown did not cause alterations in Neu-induced tumors; mammosphere formation, which is a measure of tumor-initiating capacity, is lower in Neu tumors but is not decreased by the knockdown of Id1 and Id3." (PMID 41303422, 2025). "Considering the alterations in PRMT2 that influence the transcription of ID1, ID2, and ID3, we demonstrated that PRMT2 may also regulate the tumour stemness of OSCC." (PMID 40078091, 2025). "Id1 and Id3 expression, which reflect an immature stage, is observed in the tumor cells of Wnt-1-driven tumors but not in Neu-induced tumor cells." (PMID 41303422, 2025). "ID3 represents a prominent target gene of bone morphogenetic protein (BMP) signaling, thereby highlighting the potential for exploiting BMP signaling agonists to enhance the efficacy of tumor immunotherapy." (PMID 39220104, 2024). "Furthermore, ectopic expression of ID3 in hiPSC-Macs also increased their production of the chemokines CCL3, CCL4 and CCL5, and the cytokines IL-12, IL-15 and IL-18 in response to tumour cells in vitro." (PMID 38326607, 2024). "The existence of matrix in tumor tissue and higher tumor purity were solely indicated by the high expression of ID3, which did not imply a connection with the aggressiveness of ESCC." (PMID 39256364, 2024). "We stained the tumor-infiltrating CAR T cells for TCF1, TBET, EOMES, GATA3, ID2, ID3 and IRF4." (PMID 37945901, 2023). "Moreover, S100P-SPP1 + iCCApps harbors tumor cells at different status of differentiation, such as ALB + hepatocyte differentiation and ID3+ stemness." (PMID 35347134, 2022). "Indeed, TGFβ1 and IL4 act as Id3 transcriptional repressors, which results in E-protein- and GATA-3-mediated activation of the IL9 gene transcription and even in enhanced anti-tumor response of the T cells in a melanoma mouse model." (PMID 28122577, 2017). "Id1/Id3 double knockout results in the lack of the tumor-initiating potential and increases the sensitivity of CSCs to the chemotherapeutic agent oxaliplatin." (PMID 28122577, 2017). "In other mouse and human tumor cell lines Id2 was not dominant whereas Id1 and/or Id3 were (unpublished data)." (PMID 26079374, 2015).
tumor (continued). "There were slightly stronger expression of TNC and ICAM1 in the seeding-positive tumors, but the immunopositive areas were restricted to tumor stroma rather than tumor cell clusters where the majority of ID3-immunoreactivity was found." (PMID 23768125, 2013). "PFS also showed differences in favor of patients showing no Id1/Id3 tumor co-expression although a statistical significance was not achieved (30 months vs 1 month, p = 0.219)." (PMID 23311395, 2013). "Mice lacking Id1 and Id3 genes (Id1+/−Id3−/−) are resistant to xenotransplanted tumour grafts and show defects in tumour neoangiogenesis." (PMID 20842131, 2010). "As FOXO1, ID3 and TCF7 contribute to the formation of memory T cells that home to secondary lymphoid tissues, we investigated whether CAR T cells overexpressing transcriptional regulators would exhibit enhanced trafficking to tumour dLNs." (PMID 38600376, 2024). "However, by comparing the inhibition rate, the inhibition of the Id3 KD group was more obvious regardless of tumor volume or tumor weight." (PMID 37170184, 2023). "Id1, Id2 and Id3 may increase MMP gene expression, leading to tumor cell invasion." (PMID 28122577, 2017). "Although Id1, Id2 and Id3 were highly over-expressed in SCLC in our previous work, it is not known what exact roles they may play in SCLC cells and whether they can be used as a joint or separate treatment targets for tumor suppression." (PMID 25061504, 2014). "However, for those patients with tumor samples showing an exclusive Id1 expression in the absence of Id3 expression, no impact of that expression on clinical outcomes was observed." (PMID 23311395, 2013). "Firstly, the response rate (RR) achieved with the treatment seemed to be lower among patients showing a tumor Id1/Id3 co-expression compared to those showing no Id1/1d3 co-expression with a trend towards statistical significance using the MacNemar’s test, (RR = 50% vs 87.5%, respectively; p = 0.07)." (PMID 23311395, 2013). "Moreover, mice lacking Id1/Id3 genes are resistant to tumour neoangiogenesis and tumour cells failed to grow and/or metastasize." (PMID 23555842, 2013). "Although we found that IL-7R, PLD4, and ID3 are differently expressed in human PBMC of PDAC patients, the functional role of marker-expressing immune cells, spatiotemporal relationship of the markers in tumor development, and precise mechanisms for marker upregulation remain unclear." (PMID 37165046, 2023). "Additionally, the PFS analysis showed similar differences in favor of patients lacking Id1/Id3 co-expression in their tumor samples, although the limited number of patients included could have accounted for the lack of statistical significance observed." (PMID 23311395, 2013). "In addition to this non-cognate, or innate, activation of lymphoid cells, ID3-dependent engulfment of tumour cells may also regulate cross-presentation of tumour antigens by macrophages to T cells, although KCs have been consistently shown to be poor cognate antigen-presenting cells." (PMID 38326607, 2024).
cancer (78 papers, 2007 to 2026). A tumor composed of atypical neoplastic, often pleomorphic cells that invade other tissues. "ID3 expression was correlated with cancer associated fibroblasts (CAFs) and poor prognosis, which is consistent with the theory that cancer stemness is associated with poor disease outcome." (PMID 36980203, 2023). "Alterations of the ID3 gene such as amplifications, deletions and mutations have been identified in several types of cancers." (PMID 34718742, 2021). "Consistently, analyses of TCGA cancer patient data demonstrate that low ID3 expression is associated with impaired HR." (PMID 34718742, 2021). "For example, ID3 underwent multiple duplications, but all paralogs contain the cancer risk region, which indicates that the region emerged prior to the duplication." (PMID 32731489, 2020). "Consistent with earlier studies, this study indicated that PA increase is associated with up-regulation of ID1, ID2, and ID3 mRNA expression and therefore inhibition of cancer cell differentiation." (PMID 30455990, 2018). "Inhibition of BMP signaling with the selective antagonist DMH2 caused a decrease in the expression of Id1/Id3 and induced significant growth inhibition of cancer cells expressing Oct4 or nestin." (PMID 24160469, 2013). "Together, increased Id1 and Id3 expression is observed in many cancers and is associated with poor prognosis." (PMID 23342268, 2012). "Increased proliferation is a well-established hallmark of cancer cells that is known to be regulated by Id1 and Id3." (PMID 23342268, 2012). "Of all the four Id proteins, the expression of Id1, Id2, and to a lesser extent, Id3 in cancer and the underlying molecular mechanism is relatively well known." (PMID 23342267, 2012). "Importantly, the upregulated expression of CREB3L1 and BCAS1 and downregulated expression of ID1 and ID3 appeared least impacted by the co-existing 2nd (cancer) pathway variants based on visualisation of the heat maps." (PMID 40348815, 2025). "Additionally, there are several aME genes whose dysregulation is associated with cancers when misregulated, such as Mmp14, Nid1, Mdm2, Cd36, and Id3." (PMID 41223055, 2025). "Similarly, factors M1, M47 and M48 associated with signatures SBS4, DBS2 and ID3 found in cancers related to tobacco smoking, and factor M12 with homologous recombination DNA repair deficiency related signatures SBS3 and ID6." (PMID 37420249, 2023). "In patients with LGG, Thym, DLBC and COAD, we also found at least one subgroup of patients with low ID3 expression and low HR enrichment score, indicating that low ID3 expression in specific subgroups of cancer patients is associated with impaired HR-related pathways." (PMID 34718742, 2021). "Among four types of Id proteins (Id1, Id2, Id3, and Id4), Id1 has been extensively studied in various cancers and is linked to tumorigenesis, as aberrant elevation of Id1 has been found in over 20 types of human cancer." (PMID 24970809, 2014). "Constant deregulation of Id1 and Id3 has been implicated in a wide range of carcinomas." (PMID 25061504, 2014). "Given that ID3 is downstream of C/EBPβ and loss of ID3 expression increases myogenin expression and promotes myogenic differentiation, we asked if the knockdown of ID3 could rescue differentiation in an in vitro cancer cachexia model." (PMID 30413755, 2018). "The synthetic lethality observed between ID3 loss and Class I HDAC inhibition underscores a novel therapeutic vulnerability in ID3-deficient cancers, driven by compounded defects in chromatin remodeling, cell cycle, and DNA repair." (PMID 41735198, 2026). "The expression profiles of BDP1, CLEC11A, and ID3 genes in cancer cells were detected using qRT-PCR technology." (PMID 40607387, 2025). "In short, ID3 has a regulatory role in a variety of cancers, acting as a bridge in the immune system." (PMID 39256364, 2024).
cancer (continued). "To explore the association between ID1 and ID3 expression and overall survival, we utilised data from the TARGET Pan-Cancer cohort available in the TCGA database, focusing on B-ALL." (PMID 39676870, 2024). "As a member of the ID protein family, ID3 plays an important role in cell proliferation, differentiation, and senescence and is involved in metastasis and angiogenesis of malignant tumors." (PMID 39281062, 2022). "ID3 is an inhibitor of basic helix−loop−helix (bHLH) transcription factors and has essential roles in cancer stem cell renewal and drug resistance." (PMID 35406487, 2022). "Mechanistically, we identified the Inhibitor of DNA binding 1 and 3 (ID1, ID3), drivers of cancer stemness and plasticity, as previously uncharacterized targets of transcriptional repression by ZNF148." (PMID 36207293, 2022). "ID3 expression in normal tissues is typically low or undetectable, making this protein an attractive therapeutic target in cancer." (PMID 35187538, 2021). "ID3 belongs to the ID proteins that contribute to cancer development, stemness, and metastasis, but depending on the cancer type." (PMID 34462424, 2021). "In virtually all of these cancer types the presence of ID1 and/or ID3 is associated with an aggressive phenotype and poor clinical outcome." (PMID 34031428, 2021). "The expression of known cancer-related genes such as Sostdc1, S100a4, Crabp2, and Id3 was significantly upregulated in the cancer stem-like cell cluster." (PMID 34785704, 2021). "Several novel genes including Sostdc1, S100a4, Crabp2, and Id3 were identified among the top upregulated genes in the cancer stem-like cell population." (PMID 34785704, 2021). "In TNBC subtype, basic helix-loop-helix (bHLH) transcription factors inhibitor of differentiation 1 (ID1) and inhibitor of differentiation 3 (ID3) (referred to as Id) play a vital role in maintaining cancer stem cell (CSC)." (PMID 35111680, 2021). "We also included some genes from other pathways that affected patient survival time, such as Runx1 (pathway in cancer), Id3 (amino acid stimulus) and, Plaur (cytochrome c production)." (PMID 29434213, 2018). "Id1 and Id3 proteins are overexpressed in a variety of human cancers, and play critical roles in cancer development and progression." (PMID 30297743, 2018). "ID3 has been seen to interact with multiple diseases such as cancer, vascular, neurological, autoimmune, and bone diseases." (PMID 28785583, 2017). "Genetic silencing of ID1 and ID3 increases chemotherapy sensitivity in CC-ICs suggesting that these molecules allow cancer cells to be drug resistant." (PMID 28785583, 2017). "The BMP signaling pathway is a potent direct regulator of the transcription of Id1, Id2, and Id3 during development as well as in cancer cells." (PMID 27048361, 2016). "Analysis of the Oncomine® database revealed that Id3 was significantly upregulated in 83 studies and downregulated in 84 studies in which cancers were compared to normal samples (threshold P = 0.05, fold change = 1.5, accessed date 18 June 2014)." (PMID 25693514, 2015). "Overexpression of Id1 and Id3 has been correlated with an unfavorable prognosis in a variety of cancer types and a recent study suggested Id1 and Id3 co-expression was related to poor clinical outcome in stage III-N2 non-small cell lung cancer (NSCLC)." (PMID 25061504, 2014). "Self-renewal and chemotherapy resistance in cancer-initiating cells is mediate through the expression of inhibitor of differentiation/DNA binding proteins Id1 and Id3." (PMID 24160469, 2013). "The correlation between Id1 and Id3 and its functional implications have been studied in other cancers." (PMID 23311395, 2013).
cancer (continued). "In fact, elevated Id1 and Id3 protein levels have been found in vitro and by immunohistochemistry in samples of many different human carcinoma types supporting the role of both genes in carcinogenesis." (PMID 23311395, 2013). "In spite of strong sequence similarity and assumed functional redundancy, the function of Id3 in promoting a cancer phenotype now appears to be distinct from Id1." (PMID 23342268, 2012). "FOXC1 knockout followed by RNA-seq revealed that FOXC1 positively regulates many of the same genes that are overexpressed in SP cells, some of which (e.g., ABCB1 and ID3) have been shown to play a role in drug resistance and cancer stemness in previous reports." (PMID 35406487, 2022). "All these results suggested the prognostic value of ID3 expression in diverse human cancers." (PMID 36443709, 2022). "Finally, we show that loss of ID3 triggers cellular sensitivity to PARP inhibition, thus offering new therapeutic options for ID3-deficient cancers." (PMID 34718742, 2021). "This dual effect in both culture conditions suggests that ID1 and ID3 inhibition may be effective on both the attached growth in primary tumors, as well as on the detached growth of disseminated cancer cells." (PMID 32661241, 2020). "The downstream regulatory mechanism of Id3 in cancers is various." (PMID 32760207, 2020). "These included genes involved in cell death and survival processes (BCLAF1, CFLAR, CASP1, and XIAP), genes associated with proliferation-driving transcription or cancer (KLF4, LEF1, SOX4, ID3), and genes associated with inflammation (CD28, CCR7, CX3CR1 and IFNG)." (PMID 28407008, 2017). "The development of gross chromosomal abnormalities, which is a hallmark of cancer, in ID3-deficient non-transformed cells again supports the role of ID3 in maintaining chromosome stability." (PMID 29026069, 2017). "Id1 and/or Id3 may be better targets in other cancer types for inducing the attenuated, immunogenic effect observed following Id2 knock down in Neuro2a cells." (PMID 26079374, 2015). "Further, Id3 levels in cancer have been shown to be study- and/or cell type-specific." (PMID 25693514, 2015). "Since the Inhibitors of DNA binding/differentiation (Id) family members are direct mediators of the BMP signaling, and they are involved in invasion, proliferation and metastasis of cancer cells, we measured the gene expression of Id1, Id2 and Id3 in A549 by qPCR." (PMID 24603907, 2014). "How these ID proteins maintain the cancer stem-cell phenotype is not known, but the response of GCSCs to TGF-β receptor inhibitors by reducing ID1, ID3 proteins and cell surface CD44 is very important as such markers appear to be functionally linked to the cancer-initiating phenotype of GCSCs." (PMID 23998913, 2013). "Recent investigations also support the role of Id3 in cancer." (PMID 23342268, 2012). "Among those, we identified the known BMP-2 target genes Id1, Id3, Dlx2 and Hey1, and genes that could be functionally annotated to Wnt signaling, pathways in cancer or cytokine-cytokine receptor interaction and that have critical roles in osteogenesis." (PMID 21998639, 2011). "Then we investigated whether Id3 was related to cancer characteristics using the UALCAN database." (PMID 32760207, 2020). "Thus, employing Id3 as a therapeutic target requires careful evaluation, and context-specific effects should be used to inform design of therapeutics when making decisions to treat cancer patients." (PMID 25693514, 2015). "ID1 and ID3, associated with cell differentiation, angiogenesis and reported to be increased in several cancers; MAPK8 associated with cell cycle control and cell differentiation and CDC6 a protein involved in DNA replication and which has been implicated in EMT and cancer development." (PMID 25207642, 2014). "Most notably, many of these early response alterations in the cancer cells are known pro‐angiogenic transcripts, including ITGA2, CLDN12, SMAD7, MET, KLF4, ID3 and ID1." (PMID 40116596, 2025).